IL22 (interleukin 22)
Diseases named in the same sentence as IL22 in open-access papers (continued):
Sharing a sentence is not in itself a finding about the gene and the disease.
psoriasis (continued). "We initially studied the impact of tofacitinib on intracellular pathways activated in human keratinocytes by proinflammatory cytokines with a pathogenic role in psoriasis, including IFN-γ, IL-22, TNF-α, and IL-17." (PMID 30581877, 2018). "In psoriasis, IL-22 is found to be produced by dermal CD4+ but also by epidermal CD8+ TC17 and CD4+ TH22 cells, as well as Innate Lymphoid Cells, and mast cells." (PMID 30555460, 2018). "Serum levels of TNF-α, IFN-γ, IL-2, IL-6, IL-8, IL-18, IL-22, chemerin, lipocalin-2, resistin, sE-selectin, fibrinogen, complement 3, and adiponectin correlate with psoriasis and can be used as potential biomarkers for psoriasis and response to the treatment." (PMID 29416693, 2018). "Accordingly, IL22 is selectively upregulated in paradoxical psoriasis and significantly correlates with type I IFN expression." (PMID 29295985, 2018). "IL-22 is a potent pro-inflammatory cytokine upregulated in psoriasis and in other inflammatory diseases." (PMID 29572462, 2018). "IL-17 together with IL-22 produced by Th17 cells have well-documented role in psoriasis by inducing abnormal differentiation of keratinocytes." (PMID 28623375, 2018). "The level of IL-22 was positively correlated with the production of IL-22 in plasma and the severity of psoriasis, indicating that IL-22 has a significant effect on psoriasis." (PMID 29679037, 2018). "TH17 cytokines, such as IL-17A, IL-17F, and IL-22, represent the key effector cytokines in psoriasis pathogenesis as they directly drive the development of a psoriatic phenotype." (PMID 30555460, 2018). "The JAK1/JAK2/STAT1 and JAK1/TYK2/STAT3 pathways triggered by IFN-γ and IL-22, respectively, are aberrantly activated in psoriasis, as highlighted by the peculiar STAT1 and STAT3 signatures in psoriatic skin lesions." (PMID 30581877, 2018). "IL-22 and IL-17 produced by T cells in psoriasis plaques amplify the production of the antimicrobial peptide LL-37 in keratinocytes, thereby perpetuating this potential inflammatory loop." (PMID 29520279, 2018). "The pooled serum levels of TNF-α, IFN-γ, IL-2, IL-6, IL-8, IL-18, IL-22, chemerin, lipocalin-2, resistin, sE-selectin, fibrinogen and C3 were higher in psoriasis patients compared with healthy controls (all P < 0.05)." (PMID 29416693, 2018). "IL22 not only triggers a pro-inflammatory response, it also inhibits terminal differentiation of keratinocytes which is one of the characteristics of psoriasis." (PMID 30185226, 2018). "IFN-γ and IL-22 are deeply involved in the pathogenesis of psoriasis, as they boost the expression of inflammatory genes and alter proliferative and differentiative programs in keratinocytes." (PMID 30581877, 2018). "While antibodies targeting IL-17 have shown great efficacy in psoriasis, blockade of IL-22 failed to meet primary end points in clinical trials indicating distinct role for IL-17 and IL-22 in psoriasis." (PMID 30555460, 2018). "Other pro-inflammatory cytokines such as IFNγ and GM-CSF have been described to contribute to the pro-inflammatory loop in psoriasis, while IL-22 directly stimulates keratinocyte proliferation." (PMID 29980703, 2018). "Our results demonstrate that curcumin effectively inhibited proliferation and production of IFNγ, IL-17, GM-CSF and IL-22 by T cells in ex-vivo stimulated psoriasis PBMC." (PMID 29980703, 2018). "In line with this, in transgenic mice, IL-22 was sufficient to induce a skin phenotype that resembles psoriasis, and the psoriatic phenotype induced by skin injection of IL-23 was abrogated in IL-22-deficient mice." (PMID 30555460, 2018). "The compounds suppressed the expression of IL-12/IL-23 p40, IL-17A, IL-22 and IL-23 p19 in vitro, and in vivo they ameliorated psoriasis-like skin lesions, decreased IL-17A mRNA expression, and increased the expression of keratinocyte differentiation markers." (PMID 30544700, 2018).
psoriasis (continued). "Although TNF-α has been investigated in multiplestudies of psoriasis, the cytokines IL-12, IL-17, IL-19, IL-22, and IL-23 also playcentral roles." (PMID 29630472, 2018). "Two studies of the IL-22 inhibitor fezakinumab (ILV-094) in psoriasis (NCT00563524) and RA (NCT00883896) were completed several years ago with no final data released." (PMID 30319661, 2018). "Among ILC subsets expressing NKp44 are the ILC3, which express the transcription factor RORγt and upon stimulation with IL-1β and IL-23 produce both IL-17 and IL-22 and are thought to be involved in the pathogenesis of psoriasis." (PMID 29316717, 2018). "IL-22 is required for imiquimod-induced psoriasis-form skin inflammation in mice, and for Th17 cell-mediated pathology." (PMID 30544700, 2018). "The presence of CD1a-restricted T cells polarized to IL-17 and IL-22 production in lesional psoriasis is indicative of in situ antigen presentation of LCs to T cells, but formal proof of such events remains to be shown in human settings." (PMID 29520279, 2018). "CD11b+F4/80+macrophages sorted from skin tissue with IMQ-induced psoriasis-like dermatitis expressed high levels of IL-17A and IL-22 molecules." (PMID 29508278, 2018). "Transgenic mice overexpressing IL-22 develop psoriasis-like disease, which is inhibited after breeding these mice with IL-22RA1 knockout mice (but not with IL-20RA knockout mice)." (PMID 30319661, 2018). "We found that this drug totally abrogated JAK/STAT pathways activated by IFN-γ and IL-22, as evaluated in experimental in vitro and in vivo models of psoriasis." (PMID 30581877, 2018). "Clinical trials that investigate inhibitors of IL-20 (fletikumab) and IL-22 (fezakinumab) in psoriasis and RA have been terminated." (PMID 30319661, 2018). "In the IL-23/Th17 axis model of psoriasis, IL-23 is able to produce and induce Th17 cell lymphocyte activation, which subsequently releases IL-17A, IL-17C, IL-17F, IL-22 and other related pro-inflammatory cytokines." (PMID 30544700, 2018). "In the pathogenesis of psoriasis, receptors of the cytokines IL-6, IL-12, IL-21, IL-22, IL-23, IFNα, and IFNγ are of particular importance in this respect." (PMID 29963046, 2018). "Th17 cells and their downstream effector molecules, which include IL-17A, IL-22, and TNF-α, have been shown to induce keratinocyte proliferation and other hallmark features of psoriasis." (PMID 29619073, 2018). "Consistent with this, Pla2g2f deficiency in keratinocytes markedly impairs the induction of several psoriasis markers in response to IL-17A or IL-22." (PMID 30546811, 2018). "WCR significantly ameliorated development of IMQ-induced psoriasis-like dermatitis and reduced levels of Th17 cytokines (IL-17A, IL-22, and IL-23) in both serum and dorsal skin." (PMID 29619073, 2018). "STAT3 has also been implicated in inducing the expression of Keratin 17, a proposed autoantigen in psoriasis, downstream of IL-22, IL-17, and other cytokines." (PMID 29316631, 2018). "IL-22 is a relatively recent addition to the increasing list of cytokines involved in psoriasis pathogenesis, playing a prominent role in the development of the psoriatic epidermal phenotype." (PMID 29316631, 2018). "The 3D skin equivalents were incubated, up on day four for the following three days under AD like conditions (IL-4 and IL-13), psoriasis like conditions (IL-22, OSM, IL-17, and TNFα) or left untreated." (PMID 28928464, 2017). "To validate the data obtained by microarray, we performed qRT-PCR and included AD like conditions (IL-4 and IL-13 treatment) as well as psoriasis like conditions (IL-22, OSM, IL-17, and TNFα treatment) in our experimental setup." (PMID 28928464, 2017). "IL-22 from dermal CD4+ T cells is highly expressed in lesional skin of psoriasis patients, and peripheral blood levels of IL-22 correlate strongly with disease activity, although these blood levels do not predict response to therapy." (PMID 29163483, 2017).
psoriasis (continued). "Recently, studies in mouse models as well as clinical studies in humans have demonstrated that the interleukin (IL)-23/IL-17/IL-22 axes are pivotal signaling pathways in psoriasis." (PMID 29046044, 2017). "In a mouse model of psoriasis induced by topical application of Imiquimod, it was found that ILC3s are a cellular source of IL-17A and IL-22 that mediate the Imiquimod-induced psoriasis-like disease." (PMID 28271445, 2017). "IL-23/IL-17/IL-22 axes produced by abnormal activation of Th17 cells play key roles in pathogenesis of psoriasis that stimulate keratinocyte proliferation and secretion of other inflammatory cytokines such as TNF-α, IL-1, IL-6, and IL-8." (PMID 29046044, 2017). "While the role of IL-22 in psoriasis is generally considered to be uniformly pro-inflammatory, IL-22 also possesses regulatory and tissue protective properties in other settings." (PMID 29163483, 2017). "The γδ T cells in the skin-draining lymph node of psoriasis produce approximately 10 times more IL-17A and IL-22 than CD4 T cells." (PMID 28761880, 2017). "Gene expression profiles of the lesional psoriasis have established that psoriasis is mainly induced by IL-23 and type 17 (IL-17A, IL-17F, and IL-22) cytokines." (PMID 29295520, 2017). "In patients with psoriasis, the serum levels of IL-22 are significantly elevated in patients with psoriasis compared to normal controls." (PMID 29232931, 2017). "The fact that efforts to target IL-22 in patients with psoriasis have largely stalled perhaps attests to the challenges in targeting this cytokine which has potentially opposing roles often in the same disease." (PMID 29163483, 2017). "Interleukin-22 (IL-22) and the transcription factor Stat3 play pivotal roles in the pathogenesis of psoriasis." (PMID 28272440, 2017). "Patient-derived autoantibodies against IL-22 reduced imiquimod-induced psoriasis-like inflammation in mice." (PMID 31548517, 2017). "IL-22 and IL-17F cellular sources in psoriasis have been less studied and possibly assumed to be closely co-regulated with IL-17A." (PMID 28790368, 2017). "Because of the effect of IL-22 in skin, higher levels in both skin and serum have been related to disease worsening in patients with active psoriasis." (PMID 28855908, 2017). "Dysregulation of IL-22 is thought to contribute to the development of a number of autoimmune diseases including psoriasis but also Crohn’s disease, and rheumatoid arthritis." (PMID 29163483, 2017). "Among the diverse molecules related to this axis, tumor necrosis factor (TNF)-α, IL-23, IL-17 and IL-22 have been established as the key regulators of psoriasis based on the profound effects of biologics targeting these molecules." (PMID 29232931, 2017). "IL-22 is another Th17 cytokine that is crucial in the pathogenesis of psoriasis and both patients had psoriasis (as well as patient #7 and #9 from family 4)." (PMID 28861081, 2017). "IL-22 is elevated in the serum of patients with psoriasis, Crohn‘s disease and Guillain-Barré syndrome." (PMID 28301515, 2017). "IL-22 has a dual role in inflammation, mediating proinflammatory properties in psoriasis but protective functions in hepatitis and inflammatory bowel disease." (PMID 28301515, 2017). "The discovery that ICOSL functions as novel modulator of IL-22 responses will also open new avenues for the treatment of human inflammatory disorders including psoriasis, arthritis, and IBD." (PMID 28330898, 2017). "Il-22, a critical psoriasis-related cytokine, increases CD147 expression in vitro and in vivo through Stat3." (PMID 28272440, 2017). "Similar to the results reported for protein secretion, an increase in mRNA levels of genes related to Th17 and Th1 responses in psoriasis IL-17A, IL-22, IL-23p19, RORγt, and IL-12p40 was observed in IMQ-treated group." (PMID 28761880, 2017). "The expression of IL-22 in the psoriasis patients was significantly increased after stimulation compared with the non-stimulated CS." (PMID 28303135, 2017).
psoriasis (continued). "IL-22 can increase the expression of antimicrobial peptides that are elevated in psoriasis patients in cooperation with IL-17." (PMID 29232931, 2017). "Remarkably, a similar Lin− CD123low population was identified in control skin (CS) and importantly in psoriasis skin (PS) biopsies with the capability to express IL-22 and IL-17." (PMID 28303135, 2017). "A large number of studies have established that there were lesion-related inflammatory cytokines produced by CD8+ in tissues of patients with psoriasis, particularly IL-13, IL-17, IL-22." (PMID 28881648, 2017). "We found that SOCS3 and SOCS1 expression was reduced in vivo, in tumor lesions of BCC and SCC, as compared to other skin inflammatory conditions such as psoriasis, despite the high number of IL-22-secreting TILs." (PMID 28445952, 2017). "For instance, in psoriasis, a chronic inflammatory skin disease, IL-22 is responsible for the marked hyperplasia and altered differentiation characterizing lesional epidermis." (PMID 28445952, 2017). "Once Th17 cells are activated, they produce many mediators, including IL-17A and IL-22 which consequently induce proliferation of keratinocytes and other clinical symptoms of psoriasis." (PMID 28900461, 2017). "Evidence indicates that IL-22 expression levels are high in the blood of patients with psoriasis and that high IL-22 expression levels are strongly correlated with disease severity." (PMID 28272440, 2017). "Injection of IL-22BP neutralizing antibody, a natural IL-22 inhibitor, also reproduces the exacerbation of skin inflammation found in the mouse model of psoriasis." (PMID 29232931, 2017). "Relevant to psoriasis, IL-22 promotes keratinocyte proliferation, disrupts normal keratinocyte differentiation, and acts in concert with IL-17 to release pro-inflammatory cytokines and chemokines." (PMID 29163483, 2017). "In the recent years, it was discovered that, besides the myelomonocytic compartment, the IL-17/IL-23/IL-22 axis is also relevant in the IMQ-induced psoriasis-like skin disease." (PMID 26999594, 2016). "Overexpression of Il20, Il22 or Il24 in mice leads to the development of psoriasis-like skin lesions, and levels of IL-19, IL-20, IL-22 and IL-24 are increased in psoriatic skin." (PMID 27799070, 2016). "Dermal γδ T cells are the main producers of IL-17A and IL-22 in IMQ-induced psoriasis-like skin disease." (PMID 26999594, 2016). "In the case of psoriasis, inhibition of IL-22–IL-22R1 is recommended because the persistent regenerative role of IL-22 is pathogenetic." (PMID 27829708, 2016). "Downregulation of IL-22 results in a disturbed chemokine production, pathological inflammation, and irregular cell division in experimental models of arthritis, psoriasis, and Toxoplasma gondii-induced ileitis." (PMID 28050571, 2016). "Abnormal Th22 cell number and IL-22 expression have been determined in peripheral blood from patients with psoriasis, systemic sclerosis, and rheumatoid arthritis." (PMID 27041826, 2016). "Increased levels of frequencies of IL-22 + CD4 + T cells have been observed in patients with psoriasis, active systemic lupus erythematosus (SLE) and rheumatic arthritis (RA)." (PMID 27338754, 2016). "IL-22 is released alongside IL-17 by Th17 cells and contributes to mucosal defense and maintenance of epithelial integrity but also to the pathogenesis of psoriasis." (PMID 27249027, 2016). "Previous studies showed that Th17 cell-related cytokines, such as IL-6 and IL-22, are highly expressed in psoriasis, and their pleiotropic effects include epidermal keratinocyte hyperplasia and stimulation of blood vessel formation." (PMID 26893174, 2016). "Both IL-17 and IL-22 levels are elevated in the serum of psoriasis patients, and there is a positive correlation between serum levels of these cytokines and disease severity." (PMID 26901187, 2016).
psoriasis (continued). "IL-17 and IL-22, which are produced by Th17 cells, induce keratinocyte proliferation and inflammatory responses as part of the pathogenesis of psoriasis." (PMID 26901187, 2016). "Recently, we demonstrated that IL-17A, IL-22, and IL-6 cytokines were more elevated in serum from psoriasis patients than in heathy controls." (PMID 28042206, 2016). "Among these subpopulations, NKp44+ ILC3 were reported to contribute to the pathogenesis of psoriasis, since IL-17A- and IL-22-producing NKp44+ ILC3 were increased in both the peripheral blood and the skin of patients with psoriasis." (PMID 27158469, 2016). "Th17 cells and the cytokines secreted by them, such as IL-17A, IL-17 F, IL-22 and IL-21, play a role in numerous chronic inflammatory diseases including psoriasis." (PMID 27581210, 2016). "Th1, Th17, and IL-22-producing CD4 T cells in psoriasis and autoimmunity have recently been supposed." (PMID 26339139, 2015). "Correspondingly, psoriasis patients exhibit elevated plasma IL-22 levels that correlate with disease severity." (PMID 26474319, 2015). "IL-22 is known to induce epidermal hyperplasia and to impair keratinocyte differentiation, and is increased in chronic stages of atopic dermatitis and in psoriasis." (PMID 26390218, 2015). "We have demonstrated here, that antibiotics-mediated depletion of gut microflora in adult age in fact ameliorates severity of psoriasis induced by imiquimod, together with decreased production of IL-17 and IL-22 cytokines by skin T cells." (PMID 26416167, 2015). "Surprisingly, mice treated neonatally with these antibiotics develop exacerbated psoriasis induced by imiquimod or recombinant IL-23 injection when challenged as adults, with increased IL-22-producing γδ+ T cells." (PMID 26416167, 2015). "Wolk and colleagues previously showed that IL-22 is present at high levels in the skin of patients with psoriasis, but is undetectable in healthy skin." (PMID 26474319, 2015). "As for IL-17, IL-22 levels were similar in the two groups of patients with psoriasis at T0 (35.2 ± 9.5 in group 1 and 32.9 ± 11 in group 2, resp.)." (PMID 26090395, 2015). "The first reports on the involvement of IL-22 in physiopathology were in chronic inflammatory diseases, as psoriasis or colitis, since IL-22 contributes to tissue inflammation." (PMID 25793261, 2015). "First, treatment of model epidermis with IL-17 and IL-22 recapitulate the reduction in chemerin levels reported in affected skin from psoriasis patients." (PMID 25659101, 2015). "Antibiotic treated adult mice ameliorate imiquimod-induced psoriasis and exhibit reduced pro-inflammatory IL-17 and IL-22-producing T cells." (PMID 26416167, 2015). "Surprisingly, however, neonatally antibiotic-treated mice evoke exacerbated disease with significantly increased IL-22-producing γδ+ T cells, when psoriasis is induced in adult life." (PMID 26416167, 2015). "IL-23/Th17 axis and IL-22 have been shown critical in the chronic progression of psoriasis and atopic dermatitis." (PMID 26633653, 2015). "Several studies demonstrated that Th22 cells are increased in patients with psoriasis and that IL-22 plays a major role in several steps of the pathogenesis of the disease, including inflammation and the proliferation of keratinocytes." (PMID 26090395, 2015). "Our findings demonstrate that IL-17A, IL-22, and IL-6 serum concentrations were significantly higher in psoriasis patients than in the control group." (PMID 26351408, 2015). "The circulating LL-37 appeared to affect both INF-γ and IL-22, both of which are key cytokines in the Th1 and Th17 pathways involved in psoriasis." (PMID 25197165, 2014). "Increased activation of STAT3 (pSTAT3) has been detected in lesional skin of psoriatic patients; several cytokines upregulated in psoriasis, including IL-6, IL-20, and IL-22, signal through STAT3 activation." (PMID 25126586, 2014).